CRP (C-reactive protein)
Diseases named in the same sentence as CRP in open-access papers (continued):
Sharing a sentence is not in itself a finding about the gene and the disease.
COVID-19 (continued). "Wu established a nomogram model consisting of seven variables (age, lymphocyte, CRP, LDH, creatine kinase, urea and calcium) for severity risk prediction of COVID-19 pneumonia and classify COVID-19 patients into low-risk, medium-risk, and high-risk groups." (PMID 35493729, 2022). "Patients in Cluster 1 primarily comprised subjects with severe COVID-19 who exhibited more clinical signs and these subjects presented with higher plasma CRP and chemokine levels, including CXCL10, which is known to be involved in leukocyte trafficking." (PMID 36357381, 2022). "For example, patients with more severe COVID-19 had elevated neutrophils, C-reactive protein (CRP), procalcitonin (Pct), ferritin and fibrinogen but reduced lymphocytes compared to milder COVID-19 patients." (PMID 36335131, 2022). "We verified that the gene expression of ectonucleotidases is reduced in the whole blood of patients with COVID-19 and is negatively correlated to levels of CRP, an inflammatory marker of disease severity." (PMID 36248842, 2022). "Common biochemical parameters, such as C-reactive protein, white blood cell count or ferritin, cannot be relied upon either as their levels are increased in COVID-19 patients." (PMID 35740188, 2022). "C-reactive protein (CRP), an acute phase reactant and an active regulator of the innate immune system, is increased in COVID-19 patients and has been associated to disease severity." (PMID 36741367, 2022). "While a recent publication questioned the incremental benefit of cCP as a predictor of severe COVID-19 compared to CRP, the study used a different cCP assay, and focused on a review of 3280 ambulatory patients where only 6.8% had a final diagnosis of COVID-19." (PMID 35741134, 2022). "Serum C-reactive protein (CRP) is a critical indicator that changes considerably in patients with severe COVID-19." (PMID 36140545, 2022). "CRP and IL-6 levels were also increased in COVID-19 patients with AKI, suggesting that the inflammatory storm was stronger in COVID-19 patients with AKI than in those without AKI." (PMID 35656097, 2022). "The presence of comorbidities, high BMI, adult age, and laboratory indicators such as CRP, creatinine, and ALT/ASP rate were also introduced as the major underlying factors for readmission in COVID-19 patients in Verna's study." (PMID 35596167, 2022). "The current investigation lends credence to this finding because the CRP levels in moderate and severe COVID-19 individuals were shown to have increased by 31 and 38 times, respectively." (PMID 35891270, 2022). "In a study, IL-6 in COVID-19 patients emerged superior to other biomarkers like CRP, ferritin, and liver enzymes for predicting death, with an optimal cut-off of 200 pg·L−1, respectively." (PMID 36106257, 2022). "Subjects with the most severe form of COVID-19 (critically ill) had a lower concentration of Nrf2 that negatively correlated with the markers of hyperinflammatory response (CRP, IL-6, ferritin)." (PMID 36422196, 2022). "Previous studies in COVID-19 patients have reported that CRP levels were related to mortality with an area under the receiver operating characteristic curve (AUC) of 0.896." (PMID 36381779, 2022). "Recent studies reported high levels of sST2 in COVID-19 patients, also correlating with CRP levels, a standard marker of COVID-19 activity." (PMID 35836945, 2022). "Our study’s pooling of three RCTs delineated a significant decrease in the CRP levels in COVID-19 patients taking colchicine instead of standard therapy." (PMID 35381033, 2022). "Expectedly, inflammation accompanying SARS-CoV-2 infection was reflected by strong CRP elevation in COVID-19 patients at the beginning of hospitalization." (PMID 35495660, 2022). "It was found that CRP changes significantly at the early stages of the disease in patients with COVID-19 and patients who died from the disease had levels of serum CRP 10 times greater in comparison to those who recovered." (PMID 36140545, 2022).
COVID-19 (continued). "In a study of 2782 COVID-19 patients, high levels of C reactive protein (CRP) correlate with progression to severe cases, acute kidney injury, and all-cause mortality." (PMID 36466841, 2022). "In our study, MDW was significantly positively correlated with COVID-19 inflammatory markers including CRP, LDH, Ferritin, and Procalcitonin." (PMID 34983404, 2022). "In fact, IL-6 and the inflammatory marker C-reactive protein (CRP) have been reported to correlate with COVID-19 symptoms." (PMID 35529699, 2022). "The circulating biomarkers, including CRP, are known to interact with erythrocytes and platelets pathology, resulting in severe vasculopathy in critical COVID-19 cases." (PMID 35096087, 2022). "In our in-house control cohort, 48% of severe COVID-19 patients which developed CRP > 100 mg/L died." (PMID 35407564, 2022). "While the use of SAA as a biomarker for COVID-19 requires further research, CRP and SAA are commonly used in conjunction to monitor inflammatory diseases." (PMID 35453291, 2022). "The present study is the first pilot study showing that LCR, as the ratio of lymphocyte to CRP, can differentiate disease severity of COVID-19 patients and serve as a simple and objective assistant screening tool for admission to hospital and ICU." (PMID 36248811, 2022). "This study showed that high adherence to an healthy pattern was associated with lower CRP and ESR levels and lower risk of severe COVID-19, hospitalization, and convalescence duration in patients who recovered from COVID-19." (PMID 36082030, 2022). "It has been shown to be highly effective in hospitalized COVID-19 patients presenting with hypoxia with oxygen saturation of <92% and elevated markers of systemic inflammation, most notably CRP ≥ 75 mg/L, when administered in addition to dexamethasone." (PMID 35807123, 2022). "Our results confirm that inexpensive tests like lymphocyte count and CRP can be reliably used to follow COVID-19 patients in ICU and to support the decision to discharge patients." (PMID 35830459, 2022). "An increased leukocyte level and elevated C-reactive protein were identified as predictors of severe outcomes, and D-dimer greater than 0.5 μg/mL correlated with severe COVID-19." (PMID 36553203, 2022). "Monocyte distribution width, a cytomorphological indicator that correlates with inflammatory markers, including CRP, fibrinogen, and ferritin, has recently emerged as a valuable biomarker for severe COVID-19 and sepsis." (PMID 36213639, 2022). "Within the COVID-19-positive group, the median value of CRP, D-dimers and LDH exceeded the reference values, while the lymphocyte count was below the reference values regardless of the severity of the clinical condition of the patients." (PMID 36555872, 2022). "This study aimed to assess the effect of marked interval changes in the inflammatory marker C-reactive protein (CRP) on QTc interval in patients hospitalized with COVID-19." (PMID 35811700, 2022). "Namely, patients with increased CRP, increased LDH, or lymphopenia were found to be at high risk for severe COVID-19." (PMID 36560453, 2022). "Further and based on the results of the CACOV registry, the randomized “C-reactive protein Apheresis for Attenuation of Pulmonary, Myocardial and/or Kidney Injury in COVID-19” (CAPMYKCO; NCT04898062) trial was designed." (PMID 35407564, 2022). "The proportion of subclinical hypothyroidism was 7.23% in COVID-19 patients.Patients with NTIS had higher CRP (17.6 (2.6) vs 67.4 (7.4), p<0.001), WBC count (6.26 (0.2) vs 7.59 (0.6), p=0.001) and ESR (43.9 (2.7) vs 81.5 (8.5), p<0.001)." (PMID 36601011, 2022). "An interval QTc interval prolongation is observed with a marked elevation in CRP levels in patients with COVID-19." (PMID 35811700, 2022). "Along with our results, in COVID-19 patients, it has been proven that the release of proinflammatory cytokines, resulting from an elevated CRP, LDH, and ferritin concentration seems to be responsible for disease progression." (PMID 35685588, 2022).
COVID-19 (continued). "The coagulation profile and correlation among d-dimers, C-reactive protein levels, and COVID-19 severity has been stressed in the literature." (PMID 35337362, 2022). "One more study reported that during admission of COVID-19 patients, the levels of SpO2, lymphocyte, CRP, PCT, and LDH often determine the prognosis of severity and clinical outcome." (PMID 35455363, 2022). "Lastly, underweight patients with cirrhosis and COVID-19 were in the group with the highest risk factor for developing ACLF and ICU admission, where procalcitonin levels along with CRP, IL-6, and fibrinogen were all significant independent risk factors." (PMID 35160114, 2022). "It was previously demonstrated that key plasma inflammatory markers (IL-6 and CRP) were significantly elevated in individuals with ongoing pulmonary sequelae of COVID-19 developed after the resolution of the acute phase." (PMID 36559025, 2022). "CRP is a well-established and broadly used predictor of poor outcome for infections of any origin and therefore used in COVID-19, community acquired pneumonia and viral respiratory infections." (PMID 35622838, 2022). "Some previous studies have highlighted the role of other biomarkers such as CRP, D-dimer, ferritin, or lymphocyte count for the discrimination between mild and severe COVID-19." (PMID 35632830, 2022). "One study suggests that the risk of developing serious events increase in by 5% for each unit that increases the concentration of C-reactive protein in COVID-19 patients." (PMID 35564749, 2022). "Fifth, IL-6 and CRP are the two best performing inflammatory biomarkers to predict ICU admission or death at 30 days in patients with COVID-19." (PMID 35622838, 2022). "Meta-analysis showed a significant improvement between QFPD and CWM on the number of CRP in patients with COVID-19 (4 trials, n = 315; WMD:-4.39; 95%CI − 6.58 to − 2.20; I2 = 92%, P < 0.0001)." (PMID 36307813, 2022). "Most of the studies analyzed COVID-19 infected patients in the hospitals and established the positive correlation between clinical parameters such as high levels of D-dimer, C-reactive protein, and ferritin to the severity of infection." (PMID 35852999, 2022). "An exaggerated inflammatory response in COVID-19 leads to lymphocyte activation, neutrophilia, and an increase in C-reactive protein (CRP) and inflammatory cytokines." (PMID 35203056, 2022). "While CRP is an established marker for acute inflammation and severity in COVID-19 and other diseases, ferritin can also be regarded as an acute phase protein besides its main function of iron storing and releasing." (PMID 36499657, 2022). "Most patients had elevated inflammatory markers like CRP and ferritin, which are suggested predictors for COVID-19 severity, and are reported to correlate with d-dimer and IL-6 levels." (PMID 35059221, 2022). "In the prediction of lethal outcome multivariate regression analysis extracted as an independent predictor, only higher CRP values in the non-COVID-19 group and in the COVID-19 group: older age (p ≤ 0.001), CCS (p = 0.019) and CRP (p = 0.015)." (PMID 36422354, 2022). "Stratifying our patients according to the flare after COVID-19 vaccination, the number of organs involved, and CRP values were statistically different." (PMID 35754076, 2022). "Early reports have shown that autoimmune IgG antibodies in adult COVID-19 patients are correlated with serum levels of CRP." (PMID 34744161, 2022). "A Dutch study reported a 41.7% incidence rate of VTE in COVID-19 patients and built a linear regression model consisting of D-dimer > 9 μg/mL and CRP > 280 mg/mL, and the authors report a predicted probability of 92%." (PMID 35562677, 2022). "Among the routine hematological and inflammatory parameters, we indeed observed significant changes in the level of neutrophils, CRP and lymphocytes in severe COVID-19 patients." (PMID 36441688, 2022).
COVID-19 (continued). "In a meta-analysis of five randomized clinical trials, colchicine was found to produce a statistically significant reduction of COVID-19 severity along with a decrease in CRP levels." (PMID 36559025, 2022). "Patients with higher CRP levels on admission were more likely to have severe complications of COVID-19." (PMID 35935257, 2022). "Our results showed that CRP high levels had a significant correlation with CT features for severity in COVID-19 patients." (PMID 35893392, 2022). "Corresponding to these findings, abundant amounts of CRP and complement deposits and were found in the lungs of deceased COVID-19 patients, including mainly C1q." (PMID 35407379, 2022). "The acute-phase protein and active regulator of host innate immunity, CRP, was reported to be predictive of the need for mechanical ventilation in patients with COVID-19-related uncontrolled inflammation." (PMID 36359311, 2022). "In the present study, we detected significantly higher serum levels of measured cytokines, chemokines, and inflammatory proteins (IP-10, CRP, IFNγ, IL-10, IL-13, IL-17α, IL-23, and IL-6) in COVID-19 patients than in controls." (PMID 36554094, 2022). "A second validation analysis was done, and the 3 gene signature distinguished between bacterial and COVID-19 positive subjects with a sensitivity of 88.6% and a specificity of 94.1% also outperforming CRP levels and leukocyte count." (PMID 35186993, 2022). "As for laboratory factors, neutrophils, aspartate transaminase (AST), lactate dehydrogenase (LDH), and C-reactive protein (CRP) were suitable predictors of COVID-19 patients in need of ICU care." (PMID 36120151, 2022). "The C-reactive protein (CRP) index of the MP group was significantly higher than that of the COVID-19 group (p < 0.05)." (PMID 35125096, 2022). "Our findings indicated that patients with a CRP level ≥ 100 mg/L were more likely to develop a severe form of the disease, and are more likely to die, thus conforming that CRP is a reliable predictor of COVID-19’s severity." (PMID 36451818, 2022). "Studies in adults proved that the median CRP value correlates with the severity of COVID-19 and is an independent predictor of mortality." (PMID 36420294, 2022). "Receiver operating characteristic curves data for CRP, ferritin, D-dimer and copeptin as biomarkers of severity in COVID-19 Patients." (PMID 35350852, 2022). "Patients who experienced hepatomegaly post-COVID-19 vaccination were more likely to have thrombocytopenia (n = 2), high C-reactive protein (n = 2), high erythrocyte sedimentation rate (n = 2), and high lactate dehydrogenase (n = 2)." (PMID 36229799, 2022). "The increase in COVID-19 severity and C-reactive protein concentration positively correlated with increased concentration of the P2X7 receptor in the plasma, but not with the IL-18 cytokine." (PMID 35663992, 2022). "• Association between periodontitis and severity of COVID-19.• Possible association among periodontitis and need for ventilation.• WBC and CRP serum markers were significantly higher in patients with COVID-19 who also had periodontitis." (PMID 35224542, 2022). "CRP, which serves as an early marker of inflammation, has also been reported as an early predictor of COVID-19 severity." (PMID 36518574, 2022). "C-reactive protein (CRP), an active regulator of the innate immune system, has been related to COVID-19 severity." (PMID 36741367, 2022). "Thromboembolic complications are common in SARS-CoV-2 infections and platelet counts and inflammation marker CRP were significantly elevated in COVID-19 patients." (PMID 35064792, 2022). "Tension-type headache symptoms in patients with COVID-19 were positively correlated with inflammatory markers, CRP and IL-6." (PMID 35527821, 2022). "GDF15 in severely affected COVID-19 patients is more specific than IL-6, CRP, ferritin and D-dimer in detecting the early stage of COVID-19 severity and admission to the intensive care unit (ICU)." (PMID 36140453, 2022).
COVID-19 (continued). "Intriguingly, several pathways correlated positively to PaO2/FiO2 ratio, while inversely to at least one inflammatory marker, i.e., CRP, D-dimer, or ferritin in COVID-19 patients (p < 0.05, Spearman’s correlation)." (PMID 35625719, 2022). "The C-reactive protein/lymphocyte ratio (CLR) combined with the NLR was found to be predictive for mortality in COVID-19 patients with refractory disease admitted to the ICU." (PMID 36556258, 2022). "Some studies also identified the presence of diarrhea and significantly elevated CRP as predictors of severe disease in children with COVID-19." (PMID 35540721, 2022). "Inflammation is another common clinical symptom involved in COVID-19 patients, usually assessed via CRP." (PMID 35304437, 2022). "Accordingly, VTE risk is significantly elevated in a number of conditions associated with inflammation and elevations of plasma CRP levels, particularly surgery, obesity, sepsis, cancer, inflammatory bowel disease (IBD) and COVID-19." (PMID 36177015, 2022). "Patients containing DDR1 rs4618569 had high C reactive protein (CRP), D-dimer, ferritin, high risk of mechanical ventilation, as well as severe COVID-19 and an increase in the mortality rate." (PMID 35062298, 2022). "For our study, we chose CRP as a basic and routinely measured inflammation marker, which plays a role in determining the disease severity and is well established in COVID-19 patients." (PMID 36362687, 2022). "ESR and CRP are significantly higher in dead COVID-19 patients (median: 75 (IQR: 67.5–102.50) and 44 (IQR: 27.5–56.5), respectively) than in the other groups, p < 0.001." (PMID 36570594, 2022). "Previous studies showed that NLR, D-dimer, LDH, BUN, troponin, CRP, and PCT were risk predictors for the fatal outcome related to COVID-19." (PMID 35860737, 2022). "Accordingly, high levels of interleukin (IL)-7, IL-6, ferritin, or C reactive protein (CRP) have been detected in the plasma of individuals with severe COVID-19." (PMID 35960731, 2022). "The findings showed that compared to healthy controls, patients with COVID-19 had significantly higher levels of interleukins 1α, 2, 6, 7, 8, 10 and 15, CRP, SAA, ICAM-1, VCAM-1, CXCL10, CCL3, CCL26, IFN-γ, TNF-α, bFGF, PlGF, and Flt-1." (PMID 35958594, 2022). "Various biomarkers were investigated to distinguish COVID-19 from bacterial infections such as CRP and/or WBC." (PMID 36275812, 2022). "All examined inflammatory biomarkers (CRP, fibrinogen, serum ferritin and IL-6) were higher in patients with severe COVID-19 (p < 0.001) as well." (PMID 35330457, 2022). "The median concentrations of CRP in severe COVID-19 patients (80.9; 0.5–275.2 mg/L) were significantly higher than those in the mild cases (39.8; 0.5–221.2 mg/L)." (PMID 36441688, 2022). "Levels of Interleukin-6 (IL-6), c-reactive protein (CRP), procalcitonin, ferritin, and leukocytes were compared between COVID-19, other viral respiratory infections, and bacterial pneumonia." (PMID 35622838, 2022). "BNP, D-dimer, and CRP also showed statistical significance, with p-values of 0.0098, 0.0023, and 0.0015 during the long COVID-19 evaluation, respectively." (PMID 36614901, 2022). "In our previous study, we have found that COVID-19 patients infected with P. aeruginosa express higher levels of IL-6, CRP and PCT." (PMID 35139898, 2022). "Our data showed a significant positive correlation between MDW and various laboratory parameters linked with poor prognosis of COVID-19 including total WBC, neutrophils, liver enzymes and inflammatory markers such as CRP." (PMID 34983404, 2022). "Our results also revealed that various inflammatory biomarkers, such as WBCs, NLR, CRP, and procalcitonin, were elevated in the great majority of hospitalized COVID-19 patients." (PMID 36090992, 2022). "One adult patient presented with increased C-reactive protein (CRP) of 30.7 mg/l (norm < 5 mg/l) during COVID-19." (PMID 35331203, 2022).